NPC1 (NPC intracellular cholesterol transporter 1)
Diseases named in the same sentence as NPC1 in open-access papers (continued):
Sharing a sentence is not in itself a finding about the gene and the disease.
Obesity (continued). "NPC1 is enriched in fat cells of human adipose tissue, is elevated in obesity and affected by anti-obesity therapy." (PMID 23360456, 2013). "To assess the potential function of NPC1 in obesity, we determined its expression in abdominal white adipose tissue (WAT) in relation to obesity." (PMID 23360456, 2013). "We performed a more detailed profiling of NPC1 mRNA and protein levels in relation to obesity and mRNA in relation to regional adipose depots and cellular origin." (PMID 23360456, 2013). "The association of six European obesity-related SNPs in or near FTO, NPC1, ENPP1, NEGR1, GNPDA2 and MC4R genes with risk of obesity was tested in 1,463 school-aged Mexican children (Ncases = 514; Ncontrols = 949)." (PMID 23375129, 2013). "The present detailed study of the obesity-gene NPC1 revealed that NPC1 mRNA levels were increased in both subcutaneous and omental fat depots, enriched in subcutaneous fat and isolated fat cells and down-regulated by weight loss." (PMID 23360456, 2013). "Our interest in NPC1 was stimulated by these findings, which imply a role for NPC1 in obesity and potentially adipose metabolism." (PMID 23360456, 2013). "The correlation between NPC1 mRNA levels with BMI and waist circumference in humans clearly fits into the concept of NPC1 as an obesity gene." (PMID 23360456, 2013). "Of interest are the variants in/near five genes (PTER, NPC1, MAF, SDCCAG8 and TNKS/MSRA) that had previously been associated with obesity also using samples of individuals who were extremely overweight." (PMID 21935397, 2011). "For instance, NPC1 heterozygous (NPC1+/-) human fibroblasts have increased expression of caveolin-1, which serves as a protein marker for obesity and T2DM." (PMID 22043166, 2011). "The most recent GWAS has confirmed that the FTO gene, in addition to two other obesity susceptibility genes (MC4R and NPC1, reviewed below) are associated with childhood and adult obesity within a European population." (PMID 22043166, 2011). "Carriers of pathogenic NPC1 mutations have been described to have a negative natural selection considering obesity has been linked to infertility." (PMID 33139814, 2020). "Although polymorphisms in the NPC1 gene have been associated with obesity, impaired growth is not typically observed in NPC1 patients." (PMID 30135069, 2018). "Variation in the NPC1 protein clearly exemplifies this phenomenon with genetic penetrance beyond the orphan disorder of NP-C disease into several infectious diseases, atherosclerosis, obesity, and common neurodegenerative diseases." (PMID 28913343, 2017). "Of note, we did not report any association between the NPC1 variant and obesity or BMI variation, and this association signal remains quite controversial according to population studies." (PMID 23375129, 2013). "In both studies, we genotyped six SNPs that are known to be associated with risk of obesity in European populations: rs17782313 near MC4R; rs2815752 near NEGR1; rs7754561 near ENPP1; rs1805081 in exon 6 of NPC1; rs10938397 near GNPDA2 and rs1421085 in intron 1 of FTO." (PMID 23375129, 2013). "This variant and NPC1 haplotypes were found to modulate the risk of T2D (but not BMI or obesity) in a population from Saudi Arabia." (PMID 23153210, 2012). "Nine loci have been associated with extreme obesity at the genome-wide level, five of them influencing BMI / waist circumference as well as risk for extreme obesity (FTO, MC4R, TMEM18, MSRA, NPC1), four loci being more specific of genetic risk for extreme obesity (MAF, PTER, PRL, SDCCAG8)." (PMID 22043164, 2011). "Other obesity susceptibility variants in/near MAF, NPC1, PRL, and PTER have been identified in other GWA studies of early-onset and severe obesity, and putative associations with early life weight gain may be more expected with those variants." (PMID 20520848, 2010).
Obesity (continued). "Additionally, variation at the NPC1 locus has been associated with several fundamental challenges in medicine including aging, neurodegeneration, obesity, and viral infections, suggesting that variation at the NPC1 loci has widespread relevance beyond the rare NP-C disease." (PMID 37440478, 2023). "Interestingly, some genes associated with obesity were also associated with AD by different genetic approaches: candidate gene approach FTO, by differentially expressed genes NRXN3, NPC1, NEGR1, or by GWAS approach: LEPR, BDNF, TNFα, and MTCH2." (PMID 32982666, 2020). "This upregulation of NPC1 in liver of obese mice mimic the effect we observe in human adipose tissue and could indicate that upregulation of NPC1 in obese subjects may be part of a pathway to counteract obesity." (PMID 23360456, 2013). "Although SNPs were located on obesity-related genes, some of the genes also have a direct role in lipid metabolism including PPARG, FABP2, PLIN1, NPC1, ACSL5, and FAAH, suggesting relationships between genetics, adiposity, and plasma lipid profiles." (PMID 30581838, 2018). "Actually, obesity is a complex trait, and many genes are related to obesity, such as MC4R, MAF, and NPC1." (PMID 21651756, 2011).
viral infection (32 papers, 2012 to 2025). "NPC1’s role extends beyond genetic disorders, as it has been implicated in various viral infections." (PMID 39762312, 2025). "As proteolysis of spike proteins is an essential step for viral infection, NPC1 mutations conferred a broad resistance against filovirus, retrovirus, and togavirus." (PMID 35958432, 2022). "Furthermore, this LCMSN successfully knocked-down NPC1 expression in vitro, resulting in impaired viral infection of VSV-EBOV, a high-pandemic risk pathogen surrogate." (PMID 37105997, 2023). "Then we tested the susceptibility of the NPC1-null cells to BmNPV-EGFP virus infection, and found that the percentage of EGFP positive cells among BmNPC1-null cells as indicated by the expression of red fluorescence decreased dramatically compared to the control cells at 72 h p.i.." (PMID 31866985, 2019). "This difference may have pathogenic relevance, given that the NPC1 protein is directly involved in the pathogenesis of viral infection, and that, in viral infection, IFN-γ is a key player in the activation of the adaptive immune response against intracellular pathogens." (PMID 38254990, 2024). "Knowledge‐based docking of NPC1 onto Ebola viral glycoprotein and sequence analysis of filovirus susceptible and refractory species reveals four critical residues, H418, Q421, F502 and F504, some or all of which are likely responsible for the species‐specific susceptibility to the virus infection." (PMID 26846330, 2016). "Taken together, these results suggest that Tet binds to NPC1 and confers resistance to viral infection." (PMID 40927436, 2025). "As additional proof of the strict dependency of virus infection on NPC1 expression, we mixed NPC1 KD cells with WT Caco-2 cells at different ratios and observed that the increase in the fraction of NPC1 KD cells was accompanied by a decrease in GFP positivity." (PMID 39707537, 2024). "The protective effect of NPC1 inactivation/knockdown against viral infection was further corroborated by infecting untreated and U18666A-treated Caco-2 cells with pathogenic SARS-CoV-2 (BAVPAT-1)." (PMID 39707537, 2024). "In line, former reports already indicated a principle antimicrobial capacity of NPC1 blockage for different virus infections like hepatitis C virus, Ebola virus, Dengue virus, Pseudorabies virus, and feline coronavirus." (PMID 39183751, 2024). "NPC1’s role during viral infections has been studied pharmacologically using the hydrophobic amine U18666A and the antidepressant imipramine." (PMID 38098077, 2023). "The large endo/lysosomal membrane protein (MP) Niemann-Pick C1 (NPC1), which is involved in cellular cholesterol transport, is a crucial intracellular receptor for viral infection." (PMID 38098077, 2023). "Recently, the contribution of NPC1 to virus infection has garnered attention, and the NPC1-specific inhibitor, U18666A, has been widely used to explore the potential roles of NPC1 in viral infection." (PMID 38089700, 2023). "To confirm the suitability of the model for studying the virus-host interplay during viral infection, we treated lung tissues with the macrolide antibiotic bafilomycin A1 or the NPC1 inhibitor U18666A." (PMID 36000328, 2022). "Homozygous deletion of Npc1 also protected mice from viral infection, making NPC1 an exploitable target for COVID‐19 treatment." (PMID 35958432, 2022). "In this study, we show that after knocking out NPC1, the early stage of virus infection was greatly inhibited, mainly affecting the fusion between the viral membrane and endosomal membrane." (PMID 35867410, 2022). "In the case of COVID‐19, genetic evidence highlights the role of Niemann‐Pick disease type C1 (NPC1) gene in viral infection." (PMID 35958432, 2022). "Human immunodeficiency virus type 1 and hepatitis A virus also depend on the NPC1-mediated intracellular cholesterol trafficking pathway for productive viral infection." (PMID 35867410, 2022).
viral infection (continued). "The immune function of the NPC1 gene product is known to facilitate viral infection of mosquitoes and to be induced by DENV infection in both midgut and other tissue compartments." (PMID 31601017, 2019). "qPCR analysis showed that viral infectivity decreased significantly in NPC1-null cells at 48 and 72 h p.i. compared to that in control cells, indicating that virus infection was blunted in NPC1-null cells." (PMID 31866985, 2019). "We then use the Connectivity Map (CMap), a systematic methodology for identifying functional connections between genetic perturbations and drug actions, to screen NPC1 inhibitors, and found that bis-benzylisoquinoline alkaloids (BBAs) exhibit high efficacy in the inhibition of viral infections." (PMID 40927436, 2025). "Moreover, the percentage of apoptotic U18666A-treated Caco-2 cells was comparable to that of control and U18666A-treated mock cells, providing additional evidence of resistance to virus infection determined by NPC1 inhibition." (PMID 39707537, 2024). "In addition to these techniques, the development of haploid cell-based screening opened the opportunity to identify critical host factors for viral infections, as exemplified by NPC1 for filovirus infections or LAMP1 for LASV virus entry." (PMID 37880247, 2023). "This article provides a synopsis of NPC1’s function in viral infections and a review of NPC1 inhibitors that may be used to counteract viral infections." (PMID 38098077, 2023). "Furthermore, an examination will be conducted on the many pharmaceuticals and other compounds that inhibit NPC1 and are used in the management of viral infections." (PMID 38098077, 2023). "Importantly, NPC1 has been demonstrated to be an essential and common partner for successful viral infections of several viruses." (PMID 35081156, 2022). "Although BmNPC1 domain C plays a key role in viral infection, our failure to inhibit this domain alone to abolish infection implies that other domains of NPC1 may also be involved in viral infection." (PMID 35867410, 2022). "Taken together, our results suggest that NPC2 protein incorporated into viral particles may facilitate viral infection through promoting the interaction of BmNPV and NPC1 in the endosome, thus enhancing viral fusion and escape from endosomes." (PMID 35867410, 2022). "Likewise, several publications highlighted the relevance of NPC1 in other viral infections such as Human immunodeficiency virus type-1 (HIV)." (PMID 35081156, 2022). "In addition, there are many studies reporting the importance of these cellular proteins in a number of viral infections such as hepatitis C virus (HCV) that requires a paralog of NPC1 protein named Niemann Pick C1 like 1 (NPC1L1)." (PMID 35081156, 2022). "Strikingly, this is the same position in NPC1 at which a mutation in EhNPC1 reduces receptor binding to EBOV GP and viral infection, a phenotype that could reasonably produce a selective advantage." (PMID 26698106, 2015). "The data raise the possibility that high concentrations of cationic amphiphiles may interact at low affinity with luminal loop 2 of NPC1, thereby blocking virus infection." (PMID 26646182, 2015). "Our data showed that SLC39A9, NPC1 and viral GP could co-localized upon viral infection." (PMID 39173055, 2024). "Reduced levels of the functional NPC1 protein may also protect against some viral infections." (PMID 38952711, 2024). "Therefore, further research is required before NPC1 may be used effectively as a therapeutic target for many types of viral infections." (PMID 38098077, 2023). "NPC1 is a cholesterol transporter that interacts with Ebola virus glycoprotein priming by cathepsin L in the endolysosome and mediates virus infection with other host factors; thus, cholesterol, NPC1, GP64, or other viral proteins may cooperate to mediate BmNPV entry." (PMID 34937190, 2021).
viral infection (continued). "Our findings present well-demonstrated examples of pharmacological targeting on the NPC1-STING interface, critical immunometabolic targets, for improvement in blocking viral infections." (PMID 40927436, 2025). "Upon EBOVΔVP30-EGFP infection, NPC1 KO cells and TIM1 KO cells exhibited significant reductions (80% and 25%, respectively) in viral infection (measured by EGFP percentage), as anticipated." (PMID 39173055, 2024). "We also knocked down NPC1 in Type II human primary alveolar epithelial (HPAE II) cells by small interfering RNAs (siRNAs) and found that the authentic virus infection was inhibited by over 40-fold." (PMID 38167417, 2024). "NPC1 protein levels in the tumor and non-tumor tissues were unrelated to the etiology of chronic liver diseases, and were similar in viral infections, alcoholic liver cirrhosis, and MASH." (PMID 40722778, 2025). "Moreover, SLC39A9-Flag specifically co-precipitated with NPC1-HA and viral GP proteins upon EBOVΔVP30-EGFP infection (lane 8 vs. lane 7), further confirming their interaction in the context of virus infection." (PMID 39173055, 2024). "Knockout of NPC2 reduced the fusion efficiency of the viral membrane and host endosomal membrane, and the expression of NPC2 protein in the NPC1 knockout cell line did not promote virus infection." (PMID 35867410, 2022). "Also, editing of NPC1, NPC2, or TFE3 that functions in endolysosomes had a negligible impact on Sfull virus infection." (PMID 33574281, 2021). "Tubs I/II/III did not inhibit the viral infection, and NPC1 was not required for the infection." (PMID 38167417, 2024). "In addition, when exogenous cholesterol was added during SARS2-S pseudovirus infection of Caco2, although it slightly increased the viral infection in the WT cells, it did not rescue the viral infection in NPC1-KO cells." (PMID 38167417, 2024). "The addition of NPC2 protein in the NPC1 knockout cell lines did not promote virus infection." (PMID 35867410, 2022). "Previous studies have identified NPC1 and NPC2 as important host factors for viral infection in insect cells, although their exact role in viral infection has not yet been determined." (PMID 35867410, 2022). "Genes for the endosomal entry-specific enzyme CTSL and for regulating endolysomal trafficking and membrane fusion, such as NPC1/2 and WDR81/91, were identified and required for Sdel, but not for Sfull virus infection in A549 cells." (PMID 33574281, 2021). "In contrast NPC1 transcript abundance was unchanged in HRSV infected A549 cells compared with Mock, indicating that increased NPC1 gene expression is not a generic response to viral infection." (PMID 28240256, 2017).
Alzheimer disease (15 papers, 2012 to 2025). A progressive, neurodegenerative disease characterized by loss of function and death of nerve cells in several areas of the brain leading to loss of cognitive function such as memory and language. "Studies have indicated that there is elevated NPC1 expression in Alzheimer’s disease (AD), a phenomenon associated with disrupted cholesterol homeostasis in AD." (PMID 38731839, 2024). "Conversely, Alzheimer’s disease shows features of disturbed cholesterol metabolism with lipid deposits, which are the hallmark of NPC1." (PMID 33445799, 2021). "The Npc1−/− microglia transcriptomes from seven-week-old mice can be classified as disease-associated microglia initially described in Alzheimer disease." (PMID 32731618, 2020). "Niemann–Pick C disease is an autosomal recessive disorder caused by mutations in the NPC1 or NPC2 genes, which present clinical and neuropathological signs of Alzheimer's disease dementia." (PMID 35296367, 2022). "In terms of NPC1, with an incidence of 1/120,000 live births, such similarities are described with Alzheimer’s disease, with a prevalence of 30 million people worldwide." (PMID 33445799, 2021). "Not surprisingly, mitochondrial function and OS are hallmarks of neurodegenerative diseases such as Alzheimer ́s disease and Parkinson ́s disease, as well as NPC1." (PMID 33445799, 2021). "NPC1 disease has shown to share several pathological features with a more common neurodegenerative disorder, namely Alzheimer’s disease (AD)." (PMID 34720883, 2021). "Expression of neuroprotective genes Igf1, Gpnmb and Spp1 is increased in microglia from both NPC1 and Alzheimer disease mouse models." (PMID 32731618, 2020). "DAM were initially described in an Alzheimer disease mouse model and are thought to be neuroprotective, thus supporting the concept that subpopulations of microglia in NPC1 have neurotoxic or neuroprotective activity." (PMID 32731618, 2020). "For example, it has been shown that a decreased gene dosage of Npc1+/− mice promotes weight gain, and accelerates accumulation of amyloid-β peptide in a model of Alzheimer disease." (PMID 23977027, 2013). "Alzheimer disease and NPC1 are distinctly different diseases; however, they, like other secondary tauopathies, share some pathological features." (PMID 23144710, 2012). "TAU has been shown to be hyper-phosphorylated in both NPC1 and Alzheimer disease leading to the formation of neurofibrillary tangles (NFTs)." (PMID 23144710, 2012). "Similarities in the neurodegenerative features of NPC1 and Alzheimer disease (AD) have also been noted." (PMID 23144710, 2012). "Further studies have either failed to support the link between heterozygous NPC1 mutations and PD or support the notion of its genetic influence beyond movement disorders with reports indicating a pathogenic role in Alzheimer's disease (AD)." (PMID 34149605, 2021). "Alzheimer disease is a common neurodegenerative disorder with some pathological overlap with NPC1." (PMID 23144710, 2012). "TRPML1 and TPC2 are the primary lysosomal Ca2+ release channels, mediating the Ca2+ efflux that so often is impaired in neurodegeneration (e.g., NPC1, MLIV, Fabry, and Alzheimer's disease)." (PMID 35929194, 2022).